INS (insulin)
Diseases named in the same sentence as INS in open-access papers (continued):
Sharing a sentence is not in itself a finding about the gene and the disease.
Hyperinsulinemia (continued). "Patients with T2DM and NAFLD have more severe hyperinsulinemia, dyslipidemia and lower insulin sensitivity in hepatic and adipose tissue, compared with patients without NAFLD." (PMID 36336684, 2022). "Long-term exposure to elevated concentrations of glucose results in inappropriate secretion of insulin leading to hyperinsulinemia, which negatively affects neurons." (PMID 35661882, 2022). "Peripheral insulin resistance leading to hyperinsulinemia affects insulin signaling in the CNS, which stimulates tau phosphorylation, oxidative stress, and toxicity of Aβ, contributing to cognitive decline." (PMID 35661882, 2022). "All enrolled subjects were over-weighted and had metabolic alterations characteristic of a pre-diabetic state, including hyperinsulinemia, impaired glucose tolerance and were insulin-resistant." (PMID 35120179, 2022). "In conclusion, EA improved the components of MetS, reduced hyperinsulinemia, and improved insulin sensitivity." (PMID 36233611, 2022). "Hyperinsulinemia is higher insulin levels in blood, and it mostly happens when production of insulin is higher than its clearance." (PMID 35924049, 2022). "Tumor development usually produces chronic inflammation, an increase of insulin growth factor and hyperinsulinemia, which can lead to BC with worse prognosis." (PMID 34853980, 2022). "Chronic peripheral hyperinsulinemia is expected to cause the downregulation of insulin receptors at the NVU and reduction in the insulin entry into brain, as reflected in lower brain insulin concentration in AD patients." (PMID 35805109, 2022). "The fraction of INSR internalized during acute insulin signaling seemed to be recalibrated instead of drastically affected by hyperinsulinemia under these conditions." (PMID 34921686, 2022). "On this basis, supplementing GTE or EGCG as an adjuvant in the diet is a helpful nutritional strategy in caring for insulin‐dependent metabolic disorders, including hyperinsulinemia." (PMID 36111501, 2022). "A recent study showed that in women with PCOS, metabolic clearance of insulin is reduced, contributing to developing hyperinsulinemia, as well as that serum androgens are independent predictors of this phenomenon." (PMID 35646110, 2022). "In an experimental study, C57BL/6J mice (n = 6 or 7 per group) on a selenium-supplemented diet (0.1 and 0.4 ppm selenium) developed hyperinsulinemia and reduced insulin sensitivity." (PMID 35711534, 2022). "These experiments showcased many genes that were reprogramed by hyperinsulinemia and insulin removal." (PMID 34921686, 2022). "Paradoxically, persistent hyperinsulinemia downregulates insulin receptors at the blood-brain barrier, reducing insulin delivery to the brain." (PMID 35989823, 2022). "Pathway analysis of the transcriptomics correctly revealed broad effects of hyperinsulinemia and serum starvation on insulin signaling and FOXO signaling pathways and highlighted potential upstream transcription factors." (PMID 34921686, 2022). "Although plasma insulin is lower in the SC-fed IL-6Ra KD animals compared to Cre+/- controls, this is not observed following HF-feeding, where both genotypes exhibit hyperinsulinemia." (PMID 35470093, 2022). "Hyperinsulinemia in black African women has previously been attributed to alterations in both insulin secretion and clearance, depending on age, and/or level of glycaemia." (PMID 35225824, 2022). "IR is a complex metabolic disorder in which tissues and organs exhibit impaired glucose uptake and/or utilization together with abnormal lipolysis owing to dysfunctional insulin signaling, ultimately resulting in compensatory hyperinsulinemia." (PMID 35345486, 2022). "To further examine the direct effects of hyperinsulinemia on the proximal stages of insulin signaling, we examined INSR abundance, phosphorylation and internalization in cultured muscle cells." (PMID 34921686, 2022).
Hyperinsulinemia (continued). "Reduced leptin signaling in pancreatic beta cells due to leptin resistance leads to increased secretion of insulin (hyperinsulinemia)." (PMID 36381191, 2022). "In response to high blood glucose levels, β-cells promote insulin production and lead to hyperinsulinemia." (PMID 36230963, 2022). "Sim1- and MC4R-expressing neurons control insulin secretion by regulating autonomic tone, and deficiency of Sim1 or MC4R results in hyperinsulinemia in mice and humans." (PMID 36175420, 2022). "In contrast, male rats chronically exposed to low-dose monocrotophos showed increased islet area and insulin content in whole pancreas, which corresponds with the hyperinsulinemia observed in vivo." (PMID 35156417, 2022). "For instance, hyperinsulinemia appears to be mainly driven by reduced insulin clearance as NAFLD progresses." (PMID 36009446, 2022). "In PDA cases, hyperinsulinemia or exogenous insulin use is related to the elevated PDA incidence and increased tumor volume." (PMID 35252207, 2022). "A1–7 or GABA monotherapy reduced the area under the blood glucose curve of glucose tolerance test and insulin tolerance test, alleviated HFD-induced hyperinsulinemia, and thus improved glucose tolerance and insulin sensitivity." (PMID 36265585, 2022). "One study of 39 females with PCOS and hyperinsulinemia found that metformin administration improved clinical features of hyperandrogenism and menstrual cycles by significantly lowering insulin and total and free testosterone." (PMID 36299963, 2022). "The hyperglycaemic condition in foetus induces higher insulin secretion, resulting in hyperinsulinemia in second trimester." (PMID 36078079, 2022). "Eventually, chronic hyperinsulinemia dampens tissue sensitivity to insulin, leading to cerebrovascular damage." (PMID 35661882, 2022). "Hyperinsulinemia favors a sustained stimulus to insulin signaling pathway that drives metabolic actions, progressively inducing insulin desensitization." (PMID 36224569, 2022). "If the body becomes resistant to insulin, it continues to produce more insulin than healthy children and adolescents produce, and then hyperinsulinemia occurs." (PMID 35628058, 2022). "In support of this notion, both HIIT and EV mice showed improved insulin sensitivity and reduced basal hyperinsulinemia, highlighting the requirement for lower insulin levels to maintain glycemic control." (PMID 36499248, 2022). "Animal studies found the presence of hyperinsulinemia and insulin secretory impairments in pancreatic cancer models." (PMID 35222270, 2022). "Insulin sensitizers ameliorate hyperinsulinemia and stimulate ovulatory menstrual cycles in PCOS-like monkeys." (PMID 35269778, 2022). "Consistent with the reduction in Insr mRNA, total INSR protein abundance was robustly decreased in both 2 and 200 nM hyperinsulinemia groups in an insulin dose‐dependent manner." (PMID 34921686, 2022). "We only found one study that measured plasma insulin levels and found pronounced hyperinsulinemia in malathion-exposed farmers." (PMID 35156417, 2022). "The striking reduction in insulin-mediated glucose uptake can infer hyperinsulinemia, which in turn increases free radical production." (PMID 35725834, 2022). "This review summarizes the published clinical and experimental evidence of how insulin interacts with PDA to promote hyperinsulinemia, PDA initiation, and progression." (PMID 35252207, 2022). "IR is defined as the impaired biological response of major tissues such as adipose tissue, muscle and liver to insulin stimulation, which can damage glucose metabolism and lead to compensatory increases in β-cell insulin production and hyperinsulinemia." (PMID 36357872, 2022). "Using the two larger human cohorts, after cross‐referencing with orthologous mouse genes in our hyperinsulinemia model, we identified genes that were significantly correlated with fasting insulin and differentially expressed in our hyperinsulinemia model." (PMID 34921686, 2022).
Hyperinsulinemia (continued). "As tissues become resistant to insulin, the pancreas compensates by producing more insulin, resulting in hyperinsulinemia." (PMID 36009191, 2022). "Insulin reduces renal excretion of uric acid in the context of euglycemic hyperinsulinemia, and recent experimental studies suggested that insulin affects the expression of transporters involved in urate reabsorption." (PMID 36452893, 2022). "Acute AKT and ERK signaling in response to 2 nM acute insulin exposure was reduced by hyperinsulinemia treatment in an insulin dose‐dependent manner." (PMID 34921686, 2022). "Consistent with hyperinsulinemia seen in ALMS patients, loss of Alms1 in β-cells of zebrafish also exhibited hyperinsulinemia and an impairment in glucose-stimulated insulin secretion (GSIS)." (PMID 35832432, 2022). "It is known that hyperinsulinemia can be the end-stage manifestation of a disruption at different stages of insulin metabolism." (PMID 35711802, 2022). "The effects of prolonged hyperinsulinemia were insulin dose‐dependent from the physiological to the supraphysiological range." (PMID 34921686, 2022). "Total plasma TAG and VLDL-TAG decreased during hyperinsulinemia consistent with insulin-mediated suppression of VLDL export from the liver." (PMID 35313531, 2022). "It is generally recognized that insulin is involved in bodyweight gain through hyperinsulinemia or insulin resistance." (PMID 35452190, 2022). "Intensively fed obese bulls expressed a compensated disturbance of the insulin-glucose homeostasis reflected by euglycemic hyperinsulinemia." (PMID 36003642, 2022). "Prolonged elevated insulin exposure can reinitiate cell cycle progression in mature adipocytes; however, hyperinsulinemia promotes premature cell cycle exit leading to a senescent secretory profile, including inflammatory cytokines." (PMID 35986566, 2022). "Although a significantly greater plasma insulin response to the higher quality protein supplement was anticipated, hyperinsulinemia following consumption of the alfalfa pellet was unexpected." (PMID 35978710, 2022). "Second, T329S is associated with decreases in plasma FFA and INS levels because a high FFA level can deteriorate INS sensitivity, thus creating a vicious cycle between hyperinsulinemia and HTG levels." (PMID 35433899, 2022). "Hyperinsulinemia in a high fat diet-induced obese rat model was associated with increased AHR to vagus nerve stimulation, which was prevented by reducing serum insulin with the pancreatic β-cell toxic agent, streptozotocin." (PMID 35574481, 2022). "In prediabetic status, increased blood glucose level stimulates the pancreatic islets to produce more insulin, leading to endogenous hyperinsulinemia in the human body." (PMID 35252207, 2022). "Iron can block insulin's inhibitory impact on liver glucose synthesis and diminish insulin extraction in the liver, leading to peripheral hyperinsulinemia." (PMID 36091521, 2022). "In this study, blood glucose was clamped at the basal level and a hyperinsulinemia was produced by exogenous insulin infusion." (PMID 36568071, 2022). "Our previous discoveries on ovarian impacts of HS-induced hyperinsulinemia and a documented relationship between insulin and PRL provided the rationale for our supposition." (PMID 35772766, 2022). "These hepatocyte spheroids are insulin-sensitive if cultured with physiologic concentrations of insulin and insulin-resistant if subjected to insulin levels characteristic of chronic hyperinsulinemia." (PMID 36473871, 2022). "In the presence of a good secretory reserve in the pancreatic islets, a decrease in insulin sensitivity in the metabolic target tissues leads to compensatory hyperinsulinemia." (PMID 36289636, 2022). "Over the long term, excessive food consumption is known to stimulate insulin release, resulting in chronic hyperinsulinemia." (PMID 36326689, 2022). "Reducing hyperinsulinemia in partial insulin gene knockout mice also prevents and/or reverses diet‐induced obesity in adult mice." (PMID 34921686, 2022).
Hyperinsulinemia (continued). "The findings of this study are consistent with reports that hyperinsulinemia results from increases in insulin secretion from the pancreas." (PMID 34887529, 2022). "Liver cirrhosis can reduce insulin extraction, coupled with portal-systemic shunts, and leads to systemic hyperinsulinemia and insulin resistance." (PMID 36618937, 2022). "Although carbohydrate evokes postprandial insulin secretion and leads to hyperinsulinemia, the quantity, and quality of other macronutrients, including fat and protein, induce insulin secretion and hyperinsulinemia." (PMID 36585722, 2022). "In contrast, the Phe-induced vasoconstrictive response tended to be enhanced in the aorta of KKAy mice under hyperinsulinemia compared to the insulin-free condition of reference diet fed mice (p = 0.07), and was significantly enhanced in the POA diet fed mice." (PMID 35436932, 2022). "Overall, prolonged hyperinsulinemia and insulin removal revealed strong, reciprocal transcriptomic effects." (PMID 34921686, 2022). "IR has decreased efficiency of insulin in promoting glucose uptake and utilization for several reasons, and the body produces hyperinsulinemia through compensatory secretion of excessive insulin to maintain the stability of blood glucose." (PMID 35432468, 2022). "To date, several therapeutic strategies have been proposed for the treatment of PCOS, anti-androgens for menstrual disorders and hirsutism/acne; ovulation-stimulating agents for infertility; insulin-sensitizing compounds for hyperinsulinemia." (PMID 36060969, 2022). "Based on the obtained mean + 2 SD, we established the following insulin (and HOMA-IR) values as diagnostic cut-offs for hyperinsulinemia: Men: ≥ 8 mU/L (≥ 1.5), and Women: ≥ 10 mU/L (≥ 2.0)." (PMID 36160146, 2022). "In a high insulin-resistant state, Caucasians induce hyperinsulinemia to delay T2DM development, but Asians are susceptible to T2DM development due to low insulin secretion with small amounts of islets." (PMID 35956399, 2022). "Low-dose exposure to monocrotophos also impaired plasma insulin levels, initially causing fasting hypoinsulinemia followed by pronounced fasting hyperinsulinemia and increased glucose-induced plasma insulin levels." (PMID 35156417, 2022). "High blood sugar will stimulate the islet β cells to excrete more insulin into the blood, leading to hyperinsulinemia." (PMID 35941598, 2022). "In the 200 nM hyperinsulinemia group, basal (0 nM acute insulin) glucose uptake was higher, but the fold change of insulin‐stimulated glucose uptake was lower." (PMID 34921686, 2022). "There is evidence that ovarian tissues are stimulated to create androgen through inhibition of aromatase action by free insulin growth factors, insulin resistance, and the resulting hyperinsulinemia." (PMID 36518462, 2022). "The second study used the hyperinsulinemic‐euglycemic clamp, in which ~1 nM insulin plasma insulin was maintained for 3 h (high insulin vs. saline), which represents relatively acute hyperinsulinemia." (PMID 34921686, 2022). "The prevalence of hyperinsulinemia is quite high in the overall cohort (13.0%–46.2%), demonstrating the importance of screening for insulin response during a glucose challenge in a population presenting for PCOS and androgen excess." (PMID 36568921, 2022). "IR leads to reduced tissue sensitivity to insulin and compensatory hyperinsulinemia and then stimulates the proliferation of theca-interstitial cells to increase the production and secretion of testosterone." (PMID 36386912, 2022). "Compensatory hyperinsulinemia determines exaggerated responses in the tissues that remain sensitive to insulin, with activation of the sympathetic nervous system and the increased reabsorption of renal sodium, leading to hypertension." (PMID 35562979, 2022). "The HFD group had significantly increased fasting blood glucose and insulin levels, thereby inducing fasting hyperinsulinemia." (PMID 35565930, 2022).
Hyperinsulinemia (continued). "The fasting hyperinsulinemia was coupled with “relatively” normal fasting glucose levels supporting that the “hyper-secretion” of insulin was important for metabolic homeostasis." (PMID 36278750, 2022). "In order to maintain a normal insulin level, pancreatic beta cells secrete more insulin, resulting in hyperinsulinemia and further affecting the expression of matrix proteins related to liver cell damage, inflammation, and fibrosis." (PMID 39634308, 2022). "Both endogenous hyperinsulinemia and exogenous insulin injection promote colorectal cancer growth in rats." (PMID 35244142, 2022). "To put our results in the context of a classical insulin action, we accessed the uptake of 2‐deoxy‐D‐glucose and glycogen synthesis in this hyperinsulinemia model." (PMID 34921686, 2022). "In summary, our data show an important role for TUDCA in reducing age-induced hyperinsulinemia and its complications, pointing this bile acid as an interesting therapeutic target for the treatment of glucose-insulin disturbance in the elderly." (PMID 36564463, 2022). "al who demonstrated in peripheral tissues that the blunting of insulin signaling in the presence of hyperinsulinemia occurs primarily through accumulation of DAG." (PMID 36038539, 2022). "To test this, we incubated 3T3-L1 adipocytes in high insulin concentrations as a model of hyperinsulinemia." (PMID 36467416, 2022). "We find that prolonged elevation of ROS levels in chronic hyperinsulinemia reduces the ability of insulin to promote further incorporation of IR molecules into clusters and extends the lifetime of IR molecules within the existing clusters." (PMID 36473871, 2022). "As can be observed, only 8% of men and 6% of women with insulin above the cut-offs defined for the diagnosis of hyperinsulinemia were considered metabolically normal in our cohort." (PMID 36160146, 2022). "Our findings support the importance of interventions to lower plasma insulin levels in diabetics with cancer, and to reduce weight and consequent hyperinsulinemia, in overweight and obese cancer patients." (PMID 34554347, 2022). "There are also cases of hyperinsulinemia secondary to an excessive infusion of insulin, as in the case report presented." (PMID 35135591, 2022). "Our observations also verified the distinct responses to hyperinsulinemia on the bifurcate insulin signaling pathways." (PMID 34921686, 2022). "The mentioned effects are associated with the improvement of the basal metabolic rate, the increase in sensitivity to insulin and glucose transport and suppression of hyperinsulinemia, and the increase in the capacity of oxidation of fats." (PMID 36138845, 2022). "This resultant hyperinsulinemia can lead to resistance to insulin through insulin receptor downregulation." (PMID 35836436, 2022). "Chronic hyperinsulinemia, which is common in obese women, has an effect on cell proliferation directly by high insulin levels and indirectly by higher levels of circulating insulin growth factors (IGFs)." (PMID 36301824, 2022). "Together, these data show that insulin-dependent signaling pathways are critical for the induction of senescence by prolonged hyperinsulinemia." (PMID 35872305, 2022). "Exercise reduced insulin requirements (2-fold at 3–4 months, 3-fold at 10–12 months) and improved hyperinsulinemia." (PMID 35742478, 2022). "The amount of visceral fat is directly correlated with hyperinsulinemia and inversely correlated with insulin sensitivity." (PMID 36143440, 2022). "These include alterations in insulin signaling components as a consequence of chronic hyperinsulinemia, nutritional excess, inflammation, oxidative stress, ER stress, fatty acid accumulation, and mitochondrial dysfunction." (PMID 36473871, 2022). "Hyperinsulinemia effect was present in 1000 mg dose with insulin levels of >10 mIU/mL in fasting condition, to minimise this effect the dose is reduced." (PMID 35675226, 2022).